IRF4 (interferon regulatory factor 4)
Diseases named in the same sentence as IRF4 in open-access papers (continued):
Sharing a sentence is not in itself a finding about the gene and the disease.
lymphoma (continued). "In this study, we showed that IRF4 transcriptionally induces both PD-L1 and PD1 expression in EBV lymphoma cells and co-cultured T cells, respectively, resulting in the evasion of the PD-L1/PD1 anti-tumor T cell response." (PMID 40733503, 2025). "In our setting, we have shown in this study that IRF4 upregulates both PD-L1 in EBV lymphoma cells and PD1 in co-cultured CD4+ T cells, in agreement with its oncogenic role in EBV+ lymphomas." (PMID 40733503, 2025). "These lymphomas predominantly belong to the germinal center B‐cell (GCB) subtype and exhibit strong expression of IRF4/MUM1 protein but lack the BCL2 gene translocation." (PMID 39415926, 2024). "WGS analysis additionally identified chromosomal translocations known to be recurrent in lymphoma pathogenesis and relevant for lymphoma subtyping, namely IGH::IRF4 and BCL6 rearrangements." (PMID 37333831, 2023). "There were two cases of FL (Cases LYWS-1099 and LYWS-1133), one grade 3A with BCL2 and IRF4 rearrangements, and one transformed FL to high-grade lymphoma that in the transformation acquired MYC and IRF4 rearrangements." (PMID 37555980, 2023). "The lymphoma cells usually expressed CD45, markers of lymphocyte activation (CD30, CD38, EMA, HLA-DR) and markers of plasma cell differentiation (CD138, MUM1/IRF4)." (PMID 33906629, 2021). "The lymphoma cells are positive for HHV8 and often for MUM1/IRF4 (up to 100%), CD38 (up to 100%), CD45/LCA (>80%), CD138 (35–75%), and CD30 (>50%)." (PMID 33261174, 2020). "The expression levels of both IRF4 and CFLAR were higher in ABC than those in GCB (investigated in the Lenz Lymphoma Statistics and Zhang Lymphoma Statistics datasets, respectively)." (PMID 29992138, 2018). "Interferon regulatory factor 4 (IRF4) is central to the transcriptional network of activated B-cell-like diffuse large B-cell lymphoma (ABC-DLBCL), an aggressive lymphoma subgroup defined by gene expression profiling." (PMID 24875472, 2014). "We confirmed the correlation of IRF4 with LIMD1 and CFLAR in a panel of cell lines derived from lymphomas." (PMID 25207815, 2014). "IRF4 has been known to regulate the expression of costimulatory molecules (CD80/CD86) and MHC-class-II-dependent antigen presentation in multiple immune cell types, including dendritic cells, CD226+ macrophages, and lymphoma B cells." (PMID 40585371, 2025). "Co-culturing EBV+ JiJoye lymphoma cells with CD4+ T cells or with peripheral blood mononuclear cells (PBMCs) downregulates CD4+ T cell functions, but the depletion of IRF4 in EBV+ JiJoye lymphoma cells reduces PD1 and PD-L1 expression, and partially restores CD4+ T cell functions." (PMID 40733503, 2025). "Multiple factors, such as EZH2, c-MYC, IKZF1, IKZF3, IRF4, and CDK6, which are essential for the proliferation and survival of malignant plasma cells and lymphoma, were decreased upon treatment with PM in all tested MM and lymphoma cell lines, including MM1S, MM1R, and TMD-8." (PMID 40562746, 2025). "We next investigated whether EBV lymphoma cells can impair the immune function of PBMCs, including CD4+ T cells, through the upregulation of IRF4." (PMID 40733503, 2025). "It has been shown that higher grade lymphoma, especially FL3b, is different from lower grade FL in its cytogenetic and immunohistochemical profile such as BCL2, BCL6, MYC and IRF4, which may contribute to the development of a different TME." (PMID 37591873, 2023). "The meaning of IRF4 rearrangements in other aggressive lymphomas is not well understood and warrants further studies." (PMID 37555980, 2023). "The mean portraits reveal unique spot-like patterns of over- (colored in red) or under-expressed (in blue) gene clusters but also partly overlapping spots, e.g. between BL, mnBLL-11q and, partly, intermediate lymphoma and between DLBCL, PMBL and, partly, IRF4-LCL and FL." (PMID 31039827, 2019). "RNAi-mediated down-regulation of either Spi-B or IRF4 leads to rapid death of cultured lymphoma cells, irrespective of PU.1 co-occupancy." (PMID 25765478, 2015).
lymphoma (continued). "Amongst the analyzed lymphoma types, PEL has the highest level of IRF4." (PMID 25207815, 2014). "To examine whether EBNA3C can directly regulate the expression of IRF4, we performed Western Blot analysis on P3HR1 and Jijoye cell lines, two isogenic Burkitt's Lymphoma lines." (PMID 23658517, 2013). "The results shows the B-cell lymphoma in study has Bcl-6 negative, CD10 negative and IRF4 positive phenotype, suggesting the lymphoma in study is a non-germinal center B-cell-like diffuse large B cell lymphoma." (PMID 22848504, 2012). "Thus, exosomes secreted by EBV lymphoma cells may deliver LMP1 and present MHC antigens to the co-cultured T cells, further activating TCR that induces IRF4." (PMID 40733503, 2025). "Fluorescence in situ hybridization (FISH) analysis showed no rearrangements in BCL2, IRF4, or BCL6, and any deletion in the 1p36 region (TNFRSF14 gene), ruling out other lymphoma types." (PMID 39840177, 2024). "In addition, all lymphomas developed in OPN-/-Faslpr/lpr mice were of the ABC-DLBCL type based on the expression of BCL2, C-MYC, IRF4 and of high proliferation rate (Ki67), in absence of BCL6." (PMID 36503430, 2022).
melanoma (43 papers, 2008 to 2026). A malignant, usually aggressive tumor composed of atypical, neoplastic melanocytes. "By analyzing two independent cohorts, this study found that the IRF4 SNP was associated with a worse melanoma outcome." (PMID 40869905, 2025). "IRF4 is involved in gene expression regulation in response to cytokines and interferon: a SNP in this gene has been associated with increased risk of melanoma." (PMID 40869905, 2025). "Although genetic studies have implicated IRF4 in melanoma, how IRF4 functions in melanoma cells has remained largely elusive." (PMID 38880659, 2024). "Here, we confirmed prevalent IRF4 expression in melanoma and showed that high expression is linked to dependency in cells and mortality in patients." (PMID 38880659, 2024). "Polymorphisms in IRF (discussed in detail below) offer a unique exception as IRF4 polymorphisms lead to divergence of nevus associated and de novo melanoma risk." (PMID 36834954, 2023). "Polymorphism in a specific variant of the IRF4 gene, the rs12203592 variant, was associated with different features of melanoma histologic samples." (PMID 36834954, 2023). "Further, we intersected copy number calls from our primary melanoma data with whole‐genome CRISPR screening data to identify the transcription factor interferon regulatory factor 4 (IRF4) as a melanoma‐associated dependency." (PMID 36219477, 2023). "Several genetic loci are associated with obesity and melanoma risk, including Agouti signaling protein, interferon regulatory factor 4, peroxisome proliferator-activated receptor-coactivator 1 and vitamin D receptor." (PMID 37777736, 2023). "The IRF4 rs12203592*T allele was the melanoma-risk allele in two US studies, while it was protective in a Spanish population as well as a combined analysis of Australian, UK, and Swedish subjects." (PMID 34898573, 2021). "IRF4 rs12203592 also had nominal associations (p < 0.05) with presence of mitoses and melanoma-specific survival, as well as a borderline association (p = 0.07) with ulceration." (PMID 34898573, 2021). "Here, we report the overall positive associations of IRF4 rs12203592*T with increased log of Breslow thickness, presence of mitoses, and worse melanoma-specific survival, along with a borderline association with presence of ulceration." (PMID 34898573, 2021). "The influence of the IRF4-rs12203592 T allele has been shown to be age-dependent in a large multi-population analysis of melanoma case-control data." (PMID 32121219, 2020). "We did see heterogeneity between studies in strength of SNP association with nevus count or melanoma for four loci, most extremely for IRF4." (PMID 30429480, 2018). "For example, one study identified that SNPs of interferon regulatory factor-4 (IRF4) were associated with melanoma development." (PMID 27769064, 2016). "The subtype-specific association of the MTAP locus identifies it as a plausible candidate for the nevus-associated pathway, while the age-dependent effect of IRF4 underscores the heterogeneity of melanoma susceptibility and the complex interplay between genetic and environmental factors." (PMID 41596618, 2026). "An IRF4 SNP has been also associated to an increased risk of melanoma." (PMID 40869905, 2025). "Moreover, impaired melanoma control in the DT-treated group is associated with the partial depletion of IRF4.GFP+ T cells within the tumor." (PMID 38178902, 2023). "In particular, retinal density– and FD-lowering alleles at several PoPS-prioritized genes showed associations with higher risk of skin neoplasms, malignant melanoma, and eye cancer (IRF4/DUSP22, SLC45A2); a separate set of loci showed associations with lighter skin color (GNB2, ACTG1)." (PMID 34743558, 2022).
melanoma (continued). "An example is the IRF4 intronic variant rs12203592*T, which is associated with increased melanoma risk, increased risk of nodular melanoma, increased Breslow thickness at diagnosis, high nevus count in childhood and low nevus count in adulthood, and globular dermoscopic subtype of naevi." (PMID 33681261, 2021). "Indeed, the IRF4 gene has been implicated in melanocytic biology; the IRF4 protein was proposed as a diagnostic marker for various melanoma subtypes." (PMID 31861491, 2019). "The IRF4 gene encodes a B-cell proliferation/differentiation protein, which has been proposed as a sensitive and specific marker for conventional primary and metastatic melanomas and benign melanocytic nevi." (PMID 18483556, 2008). "For example, the specific expression of interferon regulatory factor 4 (IRF4) by intra-tumoral Tregs in melanoma, lung and liver cancers marks Tregs with superior suppressive activity compared to IRF4- Tregs." (PMID 38891091, 2024). "Accordingly, IRF4 modifies the effectiveness of pertinent epigenetic drugs on melanoma cells, a finding that encourages further studies towards therapeutic targeting of IRF4 in melanoma." (PMID 38880659, 2024). "Some of the identified lead SNPs, mapping IRF4, HERC2, and TYR, were also found to be associated with melanoma or other skin diseases in the UKBiobank." (PMID 36672889, 2023). "We utilized the qRT-PCR method to explore CCL8, CXCL13 and IRF4 expression level in melanoma A375 cell lines and HFB4 control cell line." (PMID 38155221, 2023). "Our research in melanoma-bearing Irf4GFP-DTR mice revealed a major subset of endogenous IRF4.GFP+ CD8+ TILs exhibiting high levels of PD-1, Tim-3, and TIGIT." (PMID 38178902, 2023). "In this study, we made a notable discovery that IRF4+ CD8+ TILs exhibited a more differentiated cell phenotype in melanoma-bearing Irf4GFP-DTR mice." (PMID 38178902, 2023). "SOX10 plays an important role in neural crest development and inhibits melanoma cell immunogenicity by inducing the expression of interferon regulatory factor 4 (IRF4), a negative regulator of interferon regulatory factor 1 (IRF1) transcription." (PMID 37626741, 2023). "We next validated the requirement of melanoma cells for IRF4 using the orthogonal technology of siRNA knockdown and flow cytometry to assess viability." (PMID 36219477, 2023). "Through 3 distinct adoptive cell therapy (ACT) models, we discovered the essential role of IRF4-expressing CD8+ tumor-infiltrating lymphocytes (TILs) in murine melanoma defense." (PMID 38178902, 2023). "Lastly, we examined associations of IRF4 and TCL1A genes with irAEs development in patients with melanoma receiving ICI treatment." (PMID 36505471, 2022). "Associations of IRF4 and TCL1A expression with irAEs development were verified in the melanoma cohort receiving immune checkpoint inhibitors." (PMID 36505471, 2022). "SOX10 was also found to regulate immunogenicity in melanoma through IRF4 (interferon regulatory factor 4)/MUM1, another transcription factor discovered in our dataset." (PMID 35052351, 2021). "In summary, our study mainly illustrated the role of IRF4/TEX41/miR-103a-3p/C1QB axis in melanoma cells." (PMID 34915882, 2021). "In this study, we have systematically profiled the molecular signatures associated with IRF4 expression in a subset of hematological malignancies including melanoma in which IRF4 is overexpressed." (PMID 25207815, 2014). "Last, we detected consistent subclonal deletions on 9q in both melanoma and lung samples following deletions on 15q and IRF4 gain." (PMID 25160065, 2014). "IRF4 plays an important role in cancer pathogenesis and acts as a potential marker for haematological neoplasms and malignant melanoma." (PMID 24906573, 2014). "For population based melanoma, recent large scale genome wide association studies in melanoma and naevi have discovered new common low penetrance genes (MTAP, PLA2G6, TERT and IRF4 for example) associated with both naevi number and melanoma." (PMID 23796690, 2013).
melanoma (continued). "Recent GWAS have unveiled association between SNPs or genetic variants in MC1R, TPCN2, ASIP, KITLG, SLC24A5, TYR, IRF4, OCA2/HERC2, SLC24A4, SLC45A2, TYRP1, and pigmentation as well as melanoma." (PMID 21559390, 2011). "The involvement of SOX10 in melanoma immunogenicity has been studied extensively, showing that its loss sensitizes tumor cells to T-cell mediated killing, and it is a direct transcription factor for immune molecules such as CEACAM1 and IRF4." (PMID 39237877, 2024). "Taken together, IRF4.GFP+ Pmel-1 TILs derived from ACT play an essential role in melanoma control." (PMID 38178902, 2023). "Notably, these phenotypes appeared independent of changes in MYC protein expression, an established downstream target of IRF4, suggesting MYC‐independent or a pleiotropic role for IRF4 in melanoma cell survival." (PMID 36219477, 2023). "Therefore, sustained expression of IRF4 is essential for maintaining CD8+ T cell immunity in the melanoma model, and these findings carry noteworthy implications for the advancement of more potent immunotherapies for solid tumors." (PMID 38178902, 2023). "Moreover, our findings revealed that sustained expression of IRF4 is crucial for preserving CD8+ T cell immunity against murine melanoma." (PMID 38178902, 2023). "C1QB is the diagnostic and prognostic biomarker for skin cutaneous melanoma patients, IRF4 could promote melanoma cell growth via upregulating C1QB." (PMID 37071001, 2023). "Furthermore, our findings highlight the significance of sustained IRF4 expression for maintaining CD8+ T cell immunity against melanoma." (PMID 38178902, 2023). "We therefore hypothesize that some melanoma cells may upregulate IRF4 and develop a dependency on this transcription factor such that it may represent a vulnerability that could be exploited therapeutically." (PMID 36219477, 2023). "Importantly, we observed elevated expression level of IRF4 in ICI-treated melanoma patients with irAEs." (PMID 36505471, 2022). "In brief, IRF4 raised C1QB expression in melanoma cells to facilitate cell growth." (PMID 34915882, 2021). "IRF4 up-regulated TEX41 at the transcriptional level in melanoma cells." (PMID 34915882, 2021). "Moreover, qRT-PCR was conducted to detect the expression of TEX41 after melanoma cells were transfected with pcDNA3.1-IRF4 or sh-IRF4#1/2." (PMID 34915882, 2021). "IRF4 is a gene regulated by MITF in melanocytic cells, and it was also found to have a functional variant associated with increased Breslow thickness, conferring a worse survival in melanoma." (PMID 35052351, 2021). "Among the genes considered putatively involved in chromatin remodeling, two were present as down-expressed among our DEGs, POU3F2 (transcription factor, logFC = –1.549) classified as a melanoma gene, and IRF4 (interferon, logFC = -1.833) classified as a skin neoplasma gene." (PMID 30485296, 2018). "Our results have confirmed the overexpression of IRF4 in melanoma and supported the claim that IRF4 may play an important role in the development of this cancer." (PMID 25207815, 2014). "Indeed, another group of genes, including genes of the immune system, may be implicated in melanoma onset: IL-10, IL-1β, TNF-α (tumor necrosis factor alpha), HLA (human leukocyte antigen class II) genes, and IRF4 (interferon regulatory factor 4) genes." (PMID 40869905, 2025). "Additionally, we found increased expression of IRF4 in melanoma tumours compared to non‐cancerous tissues from a range of tissue sites, suggesting IRF4 amplification could play a role in melanoma development." (PMID 36219477, 2023). "Finally, by intersecting copy number analysis of our tumour collection with genome‐wide CRISPR dependency data, we revealed a potential vulnerability driven by amplification of the transcription factor IRF4, a result with implications for our understanding of melanoma biology." (PMID 36219477, 2023).
melanoma (continued). "These ‘nevi and melanoma’ genes include BRAF, CDKN2A, MITF, some telomere length maintenance genes, and IRF4." (PMID 36834954, 2023). "The objective of this study was to explore the function of interferon regulatory factor 4 (IRF4) in antitumor CD8+ T cells using the TRAMP-C1 prostate cancer and B16F10 melanoma model." (PMID 38178902, 2023). "The heatmap was used to demonstrate the expression levels of the genes TBX21, ZNF799, HEY2, ZNF580, IRF4, CREB3, and ZNF93 during the pseudotime trajectories of four distinct subtypes of melanoma cells." (PMID 37435067, 2023). "More importantly, when we temporally deleted the Irf4 gene in antitumor CD8+ T cells after ACT, starting at 20 days after melanoma implantation, we observed compromised tumor control." (PMID 38178902, 2023). "This included the interferon regulatory factor 4 (IRF4), a transcription factor known to be induced by SOX10 that acts as a negative regulator of IRF1 to repress melanoma immunogenicity." (PMID 36434616, 2022). "Furthermore, IRF4 could modulate C1QB to affect melanoma cell growth." (PMID 34915882, 2021). "Moreover, IRF4 could facilitate melanoma cell growth via up-regulating C1QB." (PMID 34915882, 2021). "The mRNA levels of many transcriptional regulators that affect the level of pigmentation, including Sox10, Ets1, and Irf4, were also reduced while the expression of Tfap2 was strongly increased in both Melb-a melanoblasts and SK-MEL-147 melanoma cells." (PMID 32151278, 2020). "Furthermore, we discovered that IRF4 stimulated the transcription of TEX41 and induced the aberrant up-regulation of TEX41 in melanoma cells." (PMID 34915882, 2021). "IRF4-activated TEX41 sequestered miR-103a-3p and modulated C1QB to promote melanoma cell malignant behaviors, for which TEX41 might be regarded as a potential therapeutic target for melanoma." (PMID 34915882, 2021).